MDM2 (MDM2 proto-oncogene)
Diseases named in the same sentence as MDM2 in open-access papers (continued):
Sharing a sentence is not in itself a finding about the gene and the disease.
acute lymphoblastic leukemia (30 papers, 2012 to 2025). Leukemia with an acute onset, characterized by the presence of lymphoblasts in the bone marrow and the peripheral blood. "We used the E2A-PBX B-cell acute lymphoblastic leukemia cell line as an easily accessible B cell model and treated them with a MDM2 inhibitor, fixed them, and stained them with DAPI and anti-phospho NF-κB antibody." (PMID 41109218, 2025). "Previous findings based on in vitro studies showed that berberine induces apoptosis in acute lymphoblastic leukemia (ALL) cells via downregulating the MDM2 oncoprotein." (PMID 36144625, 2022). "In comparison to the clinically relevant MDM2 inhibitors, compound 4 has equal or superior anticancer activity in acute lymphoblastic leukemia cell line RS4;11 and prostate cancer cell line LNCaP, which are hypersensitive to USP7 inhibition." (PMID 32300595, 2020). "In acute lymphoblastic leukemia (ALL) MDM2 is overexpressed and CDKN2A gene is frequently deleted." (PMID 28018226, 2016). "In this study, we sought to investigate the preclinical activity of the MDM2 antagonist, Nutlin-3a, in Philadelphia positive (Ph+) and negative (Ph−) leukemic cell line models, and primary B-acute lymphoblastic leukemia (ALL) patient samples." (PMID 26887044, 2016). "One study revealed that ionizing radiation-resistant (IR-resistant) acute lymphoblastic leukemia (ALL) cells are sensitive to triptolide, which reversed IR resistance in ALL cells by inducing an MDM2-overexpressing phenotype." (PMID 39764218, 2024). "In another study, performed with acute lymphoblastic leukemia (ALL) and AML patients-derived cell lines, the sublines resistant to BCL-2 inhibitors (ABT-737 and its orally active analog ABT-263—navitoclax) or MDM2 antagonist SAR405838 were developed." (PMID 31331108, 2019). "In their recently reported study, Gu and colleagues showed interesting activity of new MDM2 inhibitors that compromise XIAP mRNA translation by targeting the MDM2 RING domain, in an acute lymphoblastic leukaemia model." (PMID 29017180, 2017).
multiple myeloma (29 papers, 2012 to 2026). "We show that high expression of MDM2 is associated with poor prognosis and enhanced drug resistance in human myeloma cell lines (HMCLs)." (PMID 35326742, 2022). "It this study, inhibition of MDM2 increased the sensitivity of resistant HMCLs and primary MM xenograft samples to bortezomib and other anti-myeloma drugs, demonstrating that MDM2 can modulate drug response." (PMID 41303785, 2025). "USP7 inhibitors such as p5091, p220077, and p50429 enhance the ubiquitination and degradation of murine double minute 2 (MDM2), thereby inducing apoptosis in bortezomib-resistant multiple myeloma (MM) cells." (PMID 40296903, 2025). "In the research of multiple myeloma, targeting an MDM2/MYC axis can trigger remarkable apoptosis and overcome drug resistance." (PMID 37291112, 2023). "Early studies discovered that MDM2 is overexpressed in MM, a phenomenon that was shown to enhance myeloma cell cycle progression, proliferation, and survival." (PMID 35326742, 2022). "To translate the findings from our MDM2 KD studies to develop novel treatments for MM, we evaluated the anti-myeloma effects of MX69." (PMID 35326742, 2022). "Another mechanism for the overexpression of MDM2 in myeloma is the epigenetic silencing of miR-192, miR-194 and miR-215." (PMID 29163849, 2017).
multiple myeloma (continued). "MDM2 gene is located at chromosome 12 and the elevated MDM2 expression in myeloma could be a result of chromosome 12 diploidy (8%) or trisomy (8%)." (PMID 29163849, 2017). "We therefore sought to determine if one of the second-generation MDM2 inhibitors, MI-63, could be active against myeloma, and if it could fit into our armamentarium in combination with other currently approved and novel agents against this disease." (PMID 25181509, 2014). "The current data provide further support for the possibility that agents targeting the MDM2 E3 ubiquitin ligase, such as MI-63, could form part of our armamentarium against myeloma." (PMID 25181509, 2014). "MDM2 may be over-expressed in some cases of multiple myeloma through mechanisms such as gene amplification or chromosomal trisomy." (PMID 25181509, 2014). "Since p21 accumulation is a part of the mechanism of action for both proteasome inhibitors and immunomodulatory agents, these findings together support the possibility that approaches targeting MDM2 could be attractive options for myeloma patients." (PMID 25181509, 2014). "This pilot study demonstrated for the first time in vivo protein expression of MDM2 in the bone marrow of patients with multiple myeloma, as well as the possible effect of bortezomib on the expression of this protein in the microenvironment of multiple myeloma." (PMID 41303785, 2025). "Furthermore, our study suggests that inhibition of MDM2 could re-sensitize drug-resistant MM cells to current anti-myeloma drugs, providing the rationale for the use of MX69 in combination therapy." (PMID 35326742, 2022). "Since MDM2 upregulation was correlated with MM drug resistance, we sought to test if depleting MDM2 could re-sensitize drug resistant MM cells to frontline anti-myeloma agents." (PMID 35326742, 2022). "For the first time, we demonstrate that MDM2 and c-Myc reciprocally regulate each other via a positive feedback loop and MX69 is an effective anti-myeloma agent that re-sensitizes drug-resistant MM cells to conventional MM therapies." (PMID 35326742, 2022). "Inhibition of MDM2 by RNAi, or by the MDM2/XIAP dual inhibitor MX69, significantly enhanced the sensitivity of resistant HMCLs and primary MM samples to bortezomib and other anti-myeloma drugs, demonstrating that MDM2 can modulate drug response." (PMID 35326742, 2022). "Inhibition of MDM2 by RNAi or by the MDM2/XIAP dual inhibitor MX69 significantly increased the sensitivity of resistant HMCLs and primary MM samples to bortezomib and other anti-myeloma drugs, demonstrating that MDM2 can modulate drug response." (PMID 35326742, 2022). "Background and Objectives: This pilot study examines the expression of MDM2 and NF-κB proteins in CD138-positive plasma cells in patients with multiple myeloma treated with bortezomib-based therapy, exploring their possible interplay and correlations with clinical and selected prognostic factors." (PMID 41303785, 2025). "UA might interact with USP7 in RPMI8226 human myeloma cells and could inhibit myeloma cell proliferation (IC50 = 6.56 μmol/L), accompanied by reductions in USP7 substrates such as MDM2, UHRF1, and DNMT1 related to the inhibition of USP7." (PMID 34835969, 2021).
multiple myeloma (continued). "Interestingly, the immunomodulating agent lenalidomide, used to treat multiple myeloma, results in the phosphorylation of GSK-3 at the same serine residues that inhibit GSK-3 phosphorylation of MDM2." (PMID 26132763, 2015).
rhabdomyosarcoma (28 papers, 2001 to 2025). A rare aggressive malignant mesenchymal neoplasm arising from skeletal muscle. "MDM2 amplification has been detected in several human adult and pediatric tumors, including pediatric rhabdomyosarcomas." (PMID 35159116, 2022). "CDK4 and MDM2 were also amplified during differentiation of myoblasts towards myotubes, in leiomyosarcoma and rhabdomyosarcoma." (PMID 29416732, 2018). "Recently, single nucleotide polymorphism genotyping of a sclerosing rhabdomyosarcoma revealed amplification within the 12q13-15 region, including the genes SAS, GLI, CDK4, and MDM2." (PMID 23766666, 2013). "Ours is the second reported case of sclerosing rhabdomyosarcoma in which MDM2 amplification has been demonstrated." (PMID 23766666, 2013). "We have analysed this further using stable transfection of the mdm2 gene into 4 well-characterised human paediatric rhabdomyosarcoma cell lines." (PMID 11742497, 2001). "Additionally, exon skipping events on MDM2 (proto-oncogene) produce the MDM2-ALT1 alternative isoform, whose expression causes accelerated tumorigenesis in rhabdomyosarcomas." (PMID 40236985, 2023). "Increased MDM2 isoforms have been observed in cisplatin-treated pediatric rhabdomyosarcoma." (PMID 29065514, 2017). "CDK4 and MDM2 were amplified in leiomyosarcoma and rhabdomyosarcoma." (PMID 26760505, 2016). "We conclude that MDM2 overexpression may be a mechanism by which multidrug resistance is regulated in some rhabdomyosarcomas." (PMID 11742497, 2001). "Activated Akt can activate or deactivate its multiple substrates, including mammalian target of rapamycin (mTOR), bcl-2 family member BAD, transcription factor forkhead homolog 1 in rhabdomyosarcoma (FKHR), Mdm2 protein, glycogen synthase kinase 3 (GSK3) and many others, via its kinase activity." (PMID 22107784, 2011). "Since rhabdomyosarcoma and peripheral malignant nerve sheath tumors, etc, can also abnormally express MDM2 and CDK4, and the sensitivity of p16 expression in DDLPS is 98%, combined detection of MDM2, CDK4, and p16 genes is often recommended to avoid misdiagnosis." (PMID 39606156, 2024). "An excisional biopsy revealed an "embryonal rhabdomyosarcoma with fusocellular areas, with negative rearrangement for gen FOXO1A, negative MDM2 (only focal positivity), and positive INI-1"." (PMID 37374040, 2023).
Thrombocytopenia (28 papers, 2015 to 2026). A reduction in the number of circulating thrombocytes. "Most Mdm2 inhibitors have shown limited efficacy in Phase I trials, with significant thrombocytopenia emerging as a dose-limiting toxicity linked to prolonged Mdm2 inhibition." (PMID 40277907, 2025). "Mdm2 haploinsufficiency in BM-MSCs resulted in genotoxic stress-associated thrombocytopenia, suggesting a functional role for Mdm2 in hematopoiesis." (PMID 36909480, 2023). "Although we observed thrombocytopenia as a significant phenotype associated with Mdm2 deficiency in MSCs after irradiation, the number of megakaryocytes did not significantly decrease." (PMID 37353528, 2023). "Clinical and preclinical data in rats and monkeys have shown that some MDM2 antagonists such as Nutlin or the RG7112 compound led to a major thrombocytopenia associated with a neutropenia or, less frequently, with a mild anemia in monkeys." (PMID 26959882, 2016). "Consistent with other clinical MDM2 antagonists, idasanutlin appears to be well tolerated but the most common adverse events include gastrointestinal toxicities and myelosuppression causing febrile neutropenia and thrombocytopenia." (PMID 38600316, 2024). "Indeed, early results from clinical trials show that two MDM2 targeting drugs cause thrombocytopenia and one drug causes apoptosis of megakaryocyte progenitor cells." (PMID 26634163, 2015). "Another benefit of combinational therapies involving MDM2 inhibitors is better control over the dose-limiting toxicities associated with MDM2 inhibitor monotherapies, particularly hematological effects such as neutropenia and thrombocytopenia, as elucidated across clinical trials." (PMID 40002221, 2025). "Delayed onset thrombocytopenia resulting from effects of MDM2 inhibition on platelet progenitors is characteristic of MDM2 inhibitors." (PMID 39510293, 2024). "One of the major reported side effects of MDM2 inhibition across different cancers has been thrombocytopenia." (PMID 35801592, 2022). "In the case of MDM2 inhibitors, the dose-limiting toxicities are hematological (neutropenia and thrombocytopenia, whereas for trametinib, the dose-limiting toxic effects include rash, diarrhea, and central serous retinopathy." (PMID 30577494, 2018). "Prevalence of anemia and thrombocytopenia in pSS patients with positive anti-MDM2 was as high as 47.6% and 23.8% respectively, significant higher than pSS patients without anti-MDM2 autoantibody." (PMID 28147328, 2017). "Our results suggest that the use of TPO or TPO mimetics to rescue MDM2 antagonist-mediated thrombocytopenia would be difficult." (PMID 26959882, 2016). "Consistent with other Mdm2 inhibitors, delayed thrombocytopenia, neutropenia, anemia, and gastrointestinal side effects were observed in patients with hematologic malignancies, though these effects were not seen in solid tumor patients, suggesting a treatment-related cause." (PMID 40277907, 2025). "It is possible that the observed differences in leukopenia and thrombocytopenia may be due to the distinct roles of Mdm2 in the regulation of megakaryocytes and white blood cells." (PMID 37353528, 2023). "In conclusion, MDM2 antagonists induced a major hematopoietic defect in vitro as well as an inhibition of all stages of megakaryopoiesis that may account for in vivo thrombocytopenia observed in treated patients." (PMID 26959882, 2016).